MAGT1 (magnesium transporter 1)
Diseases named in the same sentence as MAGT1 in open-access papers (continued):
Sharing a sentence is not in itself a finding about the gene and the disease.
colorectal cancer (3 papers, 2021 to 2024). A primary or metastatic malignant neoplasm that affects the colon or rectum. "Besides, the upregulation expression of MAGT1 has been correlated with the aggressiveness as well as poor prognosis of colorectal cancer." (PMID 35416125, 2022).
viral infections (3 papers, 2017 to 2025). "We also show that MAGT1 associates with DENV NS1 and NS4B during viral infection, suggesting that these nonstructural proteins may be targets of MAGT1 oxidoreductase activity." (PMID 28720733, 2017). "While our results indicate that MAGT1 does not modulate NS4B cysteine redox state when expressed in isolation, they do not rule out the possibility that MAGT1 modulates NS4B cysteine redox status transiently and/or in the context of authentic viral infection." (PMID 28720733, 2017).
cervical cancer (2 papers, 2023 to 2024). A primary or metastatic malignant neoplasm involving the cervix. "Additionally, MagT1 has been identified as an essential gene for cervical cancer cell proliferation, and low MagT1 expression inhibits the growth of cervical cancer cells and promotes cell apoptosis." (PMID 39200180, 2024).
combined immunodeficiencies (2 papers, 2020 to 2023). "For instance, mutations disrupting Mg2+ (MAGT1) or Ca2+ (STIM1, ORAI1) transport in lymphoid cells cause combined immunodeficiencies (CID) predominantly due to defects in functions of T cells and NK cells, rather than B cells." (PMID 37273190, 2023).
congenital disorder of glycosylation (2 papers, 2020 to 2025). Congenital disorder of glycosylation (CDG) is a fast growing group of inborn errors of metabolism characterized by defective activity of enzymes that participate in glycosylation (modification of proteins and other macromolecules by adding and processing of oligosaccharide side chains). "Advances in glycobiology have revealed that MAGT1 deficiency is a selective congenital disorder of glycosylation (CDG) that predominantly affects the immune system." (PMID 32451662, 2020).
developmental disability (2 papers, 2020 to 2022). Disorders in which there is a delay in development based on that expected for a given age level or stage of development. "Further observations expanded the phenotypic spectrum of MAGT1 deficiency to intellectual and developmental disability caused by abnormal glycosylation." (PMID 35145548, 2022). "Two patients with MAGT1 variants were reported to present with different phenotypes of intellectual and developmental disability." (PMID 35145548, 2022). "Recently, a boy with the MAGT1 missense mutation c.1068A>C, p.K356N presented with intellectual and developmental disability." (PMID 32451662, 2020). "Another child with a c.991C>T, p.R331X MAGT1 mutation, which results in complete loss of protein expression, was also described to have intellectual and developmental disability." (PMID 32451662, 2020).
epilepsy (2 papers, 2014 to 2022). A brain disorder characterized by episodes of abnormally increased neuronal discharge resulting in transient episodes of sensory or motor neurological dysfunction, or psychic dysfunction. "Hence, AEDs exerted a therapeutic effect on vasogenic epilepsy derived from endothelial CDK5 loss, which results in downregulating epilepsy‐related Phka1 and Btaf1 and upregulating synaptic function‐related Grin1 and Magt1." (PMID 35770064, 2022). "Moreover, to clarify the effects of AEDs on the mRNA levels of epilepsy‐related and synapse‐related proteins in Cdh5‐CreERT2;CDK5f/f mice, the mRNA levels of Btaf1, Phka1, Nav1, Bdnf, Magt1, and Grin1 were confirmed by qRT‐PCR." (PMID 35770064, 2022). "Together, the mRNA levels of Btaf1, Phka1, Nav1, and Magt1 were related to epilepsy." (PMID 35770064, 2022). "Accordingly, changes of synapse‐related gene (Phka1, Btaf1, Magt1, and Grin1) and aberrant alternation of NMDA receptors, PSD95, phosphorylation of CaMKII were found in the hippocampus of spontaneous epilepsy mice." (PMID 35770064, 2022).
Hypomagnesemia (2 papers, 2021). An abnormally decreased magnesium concentration in the blood. "As MagT1 mutations associate with hypomagnesemia, we included MagT1 in the list of MgTHs." (PMID 34202561, 2021).
IPEX syndrome (2 papers, 2022 to 2023). "The remaining 13 patients have NOTCH1 mutation (n = 1); ALPS-Caspase10 (n = 1); CD137 deficiency (n = 1); interleukin-37 deficiency (n = 1); IPEX syndrome (n = 1); prolidase deficiency (n = 1); PRKCD deficiency (n = 1); MAGT1 deficiency (n = 1); and unspecified immune dysregulatory disease (n = 5)." (PMID 37559153, 2023).
pancreatic adenocarcinoma (2 papers, 2021 to 2025). "The high expression of CNNM4 is also correlated with high expression of TRPM7 and MAGT1, another magnesium transporter, and this TRPM7/MAGT1/CNNM4 signature is associated with low patient survival in pancreatic adenocarcinoma." (PMID 41395111, 2025). "In pancreatic adenocarcinoma (PAAD), colon adenocarcinoma (COAD) and rectum adenocarcinoma (READ), MAGT1 and CNNM4 mRNA relative levels were increased when compared to their normal corresponding samples (p < 0.01)." (PMID 33450887, 2021).
auto-inflammatory syndrome (1 paper, 2021). "In addition, one patient was diagnosed with X-linked immunodeficiency with magnesium defect, Epstein–Barr virus infection and neoplasia due to a hemizygous MAGT1 variant; another newborn was diagnosed with auto-inflammatory syndrome caused by MVK variants." (PMID 34677667, 2021).
Hypertension (1 paper, 2009). The presence of chronic increased pressure in the systemic arterial system. "While the function of TUSC3 in placenta is unknown, its paralog, MAGT1, is believed to be associated with embryonic implantation and hypertension." (PMID 19838307, 2009).
magnesium deficiency (1 paper, 2022). A nutritional condition produced by a deficiency of magnesium in the diet, characterized by anorexia, nausea, vomiting, lethargy, and weakness. "For instance, it has been reported that magnesium deficiency caused by genetic deficiencies in MAGT1 impairs anti-virus immune response which can be restored by intracellular free magnesium supplementation." (PMID 35686730, 2022).
neutropenia (1 paper, 2026). A decrease in the number of neutrophils found in the blood. "We report an infant with XMEN who acquired a novel mutation in the MAGT1 gene, presenting recurrent severe skin infections and neutropenia after 6 months of age, which was effectively managed following aggressive anti-infective treatment and HSCT." (PMID 41624006, 2026).
peripheral nerve injury (1 paper, 2022). Injury to a peripheral nerve. "Consistent with the expression changes of MOGS, the expressions of many metabolism-associated genes, including DDOST, TUSC3, STT3A, STT3B, RPN1, MAGT1, and GANC, were elevated after peripheral nerve injury." (PMID 35575968, 2022).
WHIM syndrome (1 paper, 2023). "HPV‐related papilloma cancer is seen in WHIM syndrome or EVER1, EVER2, MST1, RHOH, MAGT1, ITK deficiencies." (PMID 37102642, 2023).
ZIKV infection (1 paper, 2019). "Immunofluorescence and electron microscopy analysis have revealed co-localization of HA-tagged MAGT1 and STT3B with DENV replication compartments, which is in line with our experiments showing recruitment of DDOST-GFP at viral replication sites during YFV, WNV and ZIKV infection." (PMID 30650657, 2019).
neoplasia (31 papers, 2012 to 2026). "High MAGT1 expression was strongly associated with advanced tumor stage, poorer histological grade, and unfavorable patient prognosis, serving as an independent risk factor for overall survival." (PMID 42006149, 2026). "X‐linked immunodeficiency with magnesium defect, Epstein–Barr virus (EBV) infection, and neoplasia (XMEN) is caused by a pathogenic variant in the magnesium transporter 1 (MAGT1) gene." (PMID 41141376, 2025). "Mg2+ was suspected as a second messenger in the X-linked human immunodeficiency with Mg2+ defect and Epstein–Barr virus infection and neoplasia (XMEN): it appeared that mutations in the MAGT1 gene were actually involved." (PMID 33450887, 2021). "XMEN disease (X-linked immunodeficiency with magnesium defect, EBV infection, and neoplasia) is a rare Inborn Error of Immunity (IEI)characterized by impaired magnesium ion transport due to mutations in the MAGT1 gene, which subsequently affects immune cell function." (PMID 41624006, 2026). "X-linked immunodeficiency with magnesium defect, Epstein–Barr virus (EBV) infection and neoplasia (XMEN) is another X-linked immunodeficiency caused by pathogenic variants in MAGT1 (OMIM #300715), encoding a magnesium channel required for the control of EBV infection and neoplasia." (PMID 34677667, 2021). "Bioinformatic analysis revealed a correlation between MAGT1 expression and altered immune cell infiltration within the tumor microenvironment." (PMID 42006149, 2026). "Hemizygous loss‐of‐function variants in the MAGT1 gene are associated with X‐linked immunodeficiency with magnesium defect, Epstein–Barr virus (EBV) infection, and neoplasia (XMEN) disease." (PMID 41141376, 2025). "For example, NIPA1 and NIPAL1 were related with poor prognosis of cancers, and MAGT1 knockdown inhibited tumor progression." (PMID 39242581, 2024). "We chose to knock out the magnesium transporter MAGT1/SLC58A1, known to be mutated in patients with a disorder called X-linked immunodeficiency with magnesium defect, EBV infection, and neoplasia (XMEN)." (PMID 36725334, 2023). "In this respect, XMEN (X-linked immunodeficiency with magnesium defect, Epstein–Barr virus (EBV) infection and neoplasia) disease is caused by mutations in the magnesium transporter MagT1." (PMID 34203904, 2021). "High MAGT1 expression also correlates with chemotherapeutic resistance, metastatic status, and tumor stage." (PMID 33450887, 2021). "Mutations in the gene encoding the magnesium transporter protein 1 (MAGT1) are causative of XMEN (X-linked immunodeficiency with magnesium defect, EBV infection, and neoplasia) syndrome." (PMID 34638238, 2021). "“X-linked immunodeficiency with magnesium defect, Epstein-Barr virus (EBV) infection, and neoplasia” (XMEN) disease is an inborn error of glycosylation and immunity caused by loss of function mutations in the magnesium transporter 1 (MAGT1) gene." (PMID 32451662, 2020). "Impaired SOCE also can result from a magnesium channel defect due to pathogenic mutations in Magnesium Transporter 1 (MAGT1), which results in X-linked immunodeficiency with magnesium defect, EBV viraemia and neoplasia (XMEN) syndrome." (PMID 32868758, 2020). "MAGT1 deficiency was shown to abrogate Mg2+ influx, leading to defective activation of phospholipase Cγ and consequently impaired responses to antigen receptor engagement in patients harboring this XMEN (X-link immunodeficiency with Magnesium defect and EBV infection and Neoplasia) disease." (PMID 33450887, 2021). "Finally, a recent study highlighted the role of impaired glycosylation in the pathogenesis of X-linked immunodeficiency with magnesium defect, Epstein–Barr virus (EBV) infection, and neoplasia (XMEN) disease, caused by hemizygous LOF mutations in the magnesium transporter 1 (MAGT1) gene." (PMID 32226610, 2020).
neoplasia (continued). "Overexpression of MagT1 has recently been shown to partially rescue the growth impairment defect of TRPM7-KO DT40 B-cells and mutations in the human MAGT1 resulted in a novel X-linked immunodeficiency with magnesium defect, Epstein–Barr virus infection and neoplasia (XMEN)." (PMID 22970223, 2012). "Additionally, fifteen genes were associated with cancer control; among these, three were related to immunity (MAGT1, RFXANK and SKAP2), two (ADGRL3 and TENM3) were related to cell adhesion, and two (ADAM11 and TEP1) were found to be tumor suppressor genes." (PMID 34107880, 2021). "Although described as necessary for disulfide-mediated cross-linking to certain STT3B-dependent peptide substrates, CXXC deletion did not impair MAGT1-dependent glycosylation in a tumor cell line model system." (PMID 32451662, 2020).
cancer (7 papers, 2020 to 2024). A tumor composed of atypical neoplastic, often pleomorphic cells that invade other tissues. "Magnesium transporter 1 (MAGT1) has been shown to be associated with several human cancers." (PMID 35071748, 2022). "Studies have shown that the expression of MAGT1 impacted the progression of cancer, and NIPA1 and NIPAL1 were related with poor prognosis." (PMID 39242581, 2024). "While very little is known about MagT1 in cancer, much more is known about TRPM7." (PMID 34067290, 2021). "Also, many targeted genes, such as ZEB1, SOX5, AKAP1, CHP1, CNBP, VEGFR, and MAGT1, play a vital function in the cell shape, movement, invasion, adhesion, and polarity formation, so as to involve in many kinds of diseases such as malignant tumors, wound healing, and so on." (PMID 32547593, 2020).
infection (4 papers, 2015 to 2025). The state of being infected such as from the introduction of a foreign agent such as serum, vaccine, antigenic substance or organism. "We also propose updating XMEN to “X-linked MAGT1 deficiency with increased susceptibility to EBV-infection and N-linked glycosylation defect” in light of these novel findings." (PMID 32451662, 2020). "The OST subunit MAGT1 and its oxidoreductase activity appeared to be essential for the infection." (PMID 41148808, 2025). "To assess whether MAGT1 was ISGylated following infection, we immunoprecipitated ISG15 and could show that there is a higher molecular weight MAGT1 complex that immunoprecipitates with ISG15." (PMID 26259872, 2015).
bacterial infections (1 paper, 2015). "MAGT1 is critical for T cell activation and patients with a deletion in the MAGT1 gene are susceptible to viral and certain bacterial infections." (PMID 26259872, 2015).
MAGT1 also shares sentences with these, for which no sentence is quoted: genetic diseases (3 papers); autoimmune lymphoproliferative syndrome (2); combined immunodeficiency (2); COVID-19 (2); -Nodal Marginal Zone Lymphoma (1); Alzheimer disease (1); Autoimmunity (1); B-cell lymphomas (1); chronic granulomatous disease (1); colon adenocarcinoma (1); developmental delay (1); diabetes (1); eosinophilia (1); hemophagocytic lymphohistiocytosis (1); hepatoma (1); Listeria infection (1); lung carcinoma (1); lymphopenia (1); multiple sclerosis (1); neurodegenerative disease (1); Obesity (1); rhabdomyolysis (1); skin infection (1); T-cell deficiency (1); Thrombocytopenia (1); upper respiratory tract infections (1); vasculitis (1); X-linked disease (1).